ENSG00000252441
Synonyms: LOC124900493
Gene: Small nucleolar RNA gene on chromosome X (115,545,637 to 115,545,717, forward strand). Ensembl gene ENSG00000252441.
Gene Ontology:
Biological process: RNA processing
Cellular component: nucleolus
Homologues: Paralogues in human: SNORA64 (68% identical), SNORA10 (49% identical), SNORA10B (48% identical).